MEN1 (menin 1)
Diseases named in the same sentence as MEN1 in open-access papers (continued):
Sharing a sentence is not in itself a finding about the gene and the disease.
adrenocortical carcinoma (8 papers, 2011 to 2026). "The most peculiar and aggressive MEN1 phenotypes associated with adrenocortical carcinoma were recently described." (PMID 33312161, 2020). "Patients with MEN1 syndrome have inactivating pathogenic variants of the MEN1 gene that increase susceptibility to parathyroid tumors, pituitary tumors, pancreatic neuroendocrine tumors, and unilateral or bilateral adrenal tumors, including adrenocortical carcinoma." (PMID 33732213, 2021). "Patients with MEN1 tend to develop aldosterone and adrenocortical cancer but are less likely to develop pheochromocytoma than those with adrenal incidentaloma." (PMID 35255927, 2022). "Herewith, we report a 31 years-old female patient with sporadic form of MEN1 in whom functioning bilateral adrenocortical carcinomas were diagnosed." (PMID 21266030, 2011). "Adrenocortical carcinoma can exhibit familial aggregation in MEN1 patients." (PMID 33312161, 2020). "The patient in the present study developed pituitary somatotroph adenomas and papillary thyroid carcinoma without the other tumors commonly associated with MEN1, such as parathyroid, intestinal pancreatic endocrine or adrenal cortical tumors." (PMID 25663877, 2015).
Anxiety (8 papers, 2014 to 2025). Intense feelings of nervousness, tension, or panic often arise in response to interpersonal stresses. "- Limited follow-up can be considered in patients with MEN1-phenotype based on FIPA, MEN4, or sporadic co-occurrence of pHPT and PIT; limited follow-up potentially reduces exposure to radiation from imaging, costs, and anxiety." (PMID 30254610, 2018).
hypoparathyroidism (8 papers, 2016 to 2024). Hypoparathyroidism is an endocrine disorder in which the parathyroid glands in the neck do not produce enough parathyroid hormone (PTH). "Nowadays, the surgery of pHPT in patients with MEN1 is oriented to subtotal parathyroidectomy or less than subtotal parathyroidectomy for the decreased risk of postsurgical hypoparathyroidism." (PMID 39795539, 2024). "As TPTX is related to the highest risk of permanent hypoparathyroidism, the current recommendations favor subtotal surgery for MEN1-related PHPT." (PMID 39575107, 2024). "The present study supports that HPT/MEN1 patients extensively explored during surgery attempting reach STPTX or TPTX+AG are in higher risk of develop hypoparathyroidism with similar frequency that observed with TPTX+AG." (PMID 30899245, 2019). "Nevertheless, we believe that our results clearly show that there is a subgroup of MEN1 patients with concordant imaging studies who could benefit from unilateral clearance with resultant lower risk of permanent hypoparathyroidism." (PMID 27402205, 2016). "The persistence of pHPT over many years often necessitates repeated resections in the lifespan of patients with MEN1, presenting a delicate balance between persistent pHPT and lifelong hypoparathyroidism in the event of excessive resection." (PMID 39795539, 2024). "The incidence of hypoparathyroidism after EA is 4.5%, which is lower than that in patients with recurrent MEN1-related PHPT after reoperation." (PMID 37795364, 2023). "The concept of limited surgery in MEN1-related PHPT was presented to overcome the permanent hypoparathyroidism after TPX." (PMID 32606444, 2020). "By less extensive surgeries, it would be possible minimize, avoid or postpone long-standing permanent hypoparathyroidism, mainly in the subset of young cases (< 50 y) that represent the age group more commonly underwent to surgical treatment in MEN1." (PMID 30899245, 2019). "However, considering the significant postoperative hypoparathyroidism rate associated with TPX and the feasibility of PVS, individualised decisions regarding the surgical extent of resection in MEN1-related PHPT is important." (PMID 32606444, 2020). "The surgical treatment of PHPT in MEN1 patients is usually a compromise between leaving non adenomatous parathyroid tissue sufficient enough to avoid a permanent hypoparathyroidism and removing all the tumor glands to prevent persistence or prompt recurrence of PHPT." (PMID 30319541, 2018). "Although TPX with auto-transplantation is the standard surgery for MEN1-related PHPT, surgical extent individualisation is necessary, given the postoperative hypoparathyroidism rate of TPX and feasibility of PVS." (PMID 32606444, 2020). "Most MEN1 patients requiring parathyroidectomy are younger than 50 years and they pose a difficult balance to achieve between persistent HPT and life-long hypoparathyroidism." (PMID 30899245, 2019). "Thus, Optimal therapeutic strategies for MEN1-related PHPT that not only possess an acceptable efficacy but also prevent the recurrence and postoperative hypoparathyroidism remain inconsistent." (PMID 37795364, 2023). "TPX may be the only curative surgery for MEN1-related PHPT; however, permanent hypoparathyroidism is a major complication that is more troubling than disease recurrence." (PMID 32606444, 2020). "For appropriately selected MEN1 patients, unilateral clearance can achieve similar results as STP and has no risk of permanent hypoparathyroidism, and may facilitate possible future reoperations." (PMID 27402205, 2016). "However, the prevalence of permanent hypoparathyroidism after STPTX is not irrelevant and it may be aggravated as most MEN1 patients are diagnosed and operated for HPT in young age (< 50 y)." (PMID 30899245, 2019).
leiomyoma (8 papers, 2021 to 2025). A well-circumscribed benign smooth muscle neoplasm characterized by the presence of spindle cells with cigar-shaped nuclei, interlacing fascicles, and a whorled pattern. "A total of 24/32 (75%) patients with genotype-positive MEN1 needed resection of their leiomyomas while the remaining patients were conservatively managed through their last follow-up." (PMID 39946193, 2025). "Nevertheless, we calculated the cumulative incidence of leiomyoma in our MEN1 patients across age groups." (PMID 37484956, 2023). "Familial MEN1 (n = 129): Uterine leiomyomas were observed in 18 (24%) out of 119 women, and such percentage was similar in both index cases and relatives." (PMID 37484956, 2023). "In both leiomyomas, there was LOH at the MEN1 locus and the authors proposed that esophageal leiomyoma is associated with alterations in the MEN1 gene." (PMID 36325452, 2022).
lung carcinoids (8 papers, 2014 to 2025). "For example, MEN1 (11–22%) is the most frequently mutated gene with somatic mutations in lung carcinoids." (PMID 35331190, 2022). "Germline mutations in MEN1 are present in approximately 2% of lung carcinoid patients, in the context of MEN1 hereditary syndrome." (PMID 35626118, 2022). "Analysis of human NET tumor samples demonstrated mutations of the MEN1 gene in up to 35% of lung carcinoids and up to 37% of pNETs." (PMID 32033025, 2020). "Homozygous somatic inactivation of the MEN1 gene has been reported in 36% of sporadic lung carcinoids." (PMID 38001701, 2023).
lung carcinoma (8 papers, 2015 to 2024). "To delineate the selective suppression of splicing inhibitors in MEN1-deficient lung cancer growth in vivo, we subcutaneously transplanted MEN1-WT and MEN1-KO NCI-H460 cells into nude mice." (PMID 37395406, 2023). "A similar phenomenon was found in Mad- and Iso-treated MEN1 knockdown A549 cells and Men1-deleted MEFs, which highlights the selective effect of splicing inhibitors in inducing the death of MEN1-deficient lung cancer cells." (PMID 37395406, 2023). "Given the roles of these changed MEN1-related exon skipping events in the progression of lung cancer, their potential as therapeutic targets specifically against MEN1-deficient cancer should be investigated in the future." (PMID 37395406, 2023). "Furthermore, we identified 28 MEN1-regulated exon-skipping events in lung cancer cells that were closely correlated with survival in patients with lung adenocarcinoma, and MEN1 deficiency sensitized lung cancer cells to splicing inhibitors." (PMID 37395406, 2023). "We further investigated whether splicing inhibitors can reverse the malignant behaviors of MEN1-deficient lung cancer cells." (PMID 37395406, 2023). "Given that MEN1 plays an important role in the regulation of RNA metabolism and genome stability, we next investigated the biological implications of MEN1-regulated ASEs in human lung cancer." (PMID 37395406, 2023). "Altogether, these findings further support the claim that MEN1-regulated ASEs have functional significance in lung cancer." (PMID 37395406, 2023). "Venn diagram analysis identified 399 conserved MEN1-regulated ASEs from the mouse lung tissue and lung cancer cells, 164 of which were SE events." (PMID 37395406, 2023). "MEN1 deletion resulted in reprogramming of AS patterns in mouse lung tissue and human lung cancer cells, suggesting that MEN1 has a general function in regulating alternative precursor mRNA splicing." (PMID 37395406, 2023). "The results indicate that Men1 deficiency gives rise to primary lung cancer and further suggest that there are multiple cellular origins of primary lung cancer attributable to Men1 deletion." (PMID 32081882, 2020). "Indeed, RT–PCR results indicated that the deletion of MEN1 in lung cancer cells increased the instances of short splicing isoforms in the FAM189B, NUBP2, ENDOV and TARBP2 genes, but inhibited generation of the CPSF7, MRRF and LETMD1 splicing isoforms." (PMID 37395406, 2023). "Men1 is an anti−oncogene in lung cancer and is expressed in low amounts in lung cancer tissues." (PMID 35628193, 2022). "Thus, Men1 would be a potential target in both primary diseases of the lung: lung cancer and pulmonary fibrosis." (PMID 35628193, 2022). "We recently found that deletion of MEN1 activated phosphorylation of CHK2 (p‐CHK2), a G2/M cell cycle checkpoint, in lung cancer cells." (PMID 35968938, 2022). "Importantly, the MEN1/MLL gene is mutated at high frequencies in certain types of human NE lung cancers, such as lung carcinoids or SCLC15,16, suggesting that menin regulation is a common characteristic in NE-type neoplasms originating from multiple organs, including NE-type lung cancer." (PMID 32081882, 2020). "Specific depletion of Men1 in ATII cells markedly accelerated the initiation and progression of KrasG12D-driven lung cancer, notably shortening the survival time of mice to 9 weeks with more aggressive behavior." (PMID 32081882, 2020).
lung NETs (8 papers, 2016 to 2025). "Interestingly, patients with germline MEN1 mutations and lung NETs have a favorable prognosis, possibly owing to early screening that identifies 86% of tumors, allowing timely curative treatment." (PMID 40026252, 2025). "Lung NETs are encountered in approximately 20% of patients with MEN1, and are potentially responsible for elevated CgA." (PMID 40455177, 2025). "The prevalence of other manifestations associated with MEN1 was gastric NET in 3.7 %, lung NET in 19.3 %, thymic NET in 4.0 %, and ADR in 31.4 % of patients." (PMID 27842554, 2016). "These tumors were enriched for mutations in cell-cycle gene ATM and chromatin remodeling genes ARID1A, MEN1, and EIF1AX, which are most observed in lung NETs." (PMID 40026252, 2025). "First, due to the rarity of lung NET, tissue availability is limited, so we could not be too restrictive by excluding patients who lacked certain clinical features, and no information on RNA sequencing or MEN1 mutation status was available." (PMID 40072638, 2025).
melanoma (8 papers, 2019 to 2025). A malignant, usually aggressive tumor composed of atypical, neoplastic melanocytes. "Characterization of the MEN1 gene in two families bearing melanoma highlighted specific MEN1 mutations, leading to loss of expression or increased degradation of the MEN1 gene product, further leading to a loss of TGFβ signaling." (PMID 38891107, 2024). "Identification of specific point mutations in MEN1 family members affected by melanoma also revealed increased MEN1 gene product degradation, leading to a loss of TGFβ signaling." (PMID 38891107, 2024). "To gain further clinical insights into the role and contribution of MEN1 in melanoma development, we identified melanoma patients harboring MEN1 mutations." (PMID 38891107, 2024). "The clinical implication is that patients should be tested for potential MEN1 gene mutations whenever 2 or more family members have developed melanoma." (PMID 38891107, 2024). "MEN1 gene-respective menin involvement has also been described in melanomas, but the association with the syndrome remains debatable." (PMID 36428828, 2022). "Genetic similarities between Spizoid nevi and melanoma were found, including mutations of the MEN1 gene." (PMID 36428828, 2022). "The study analyzed possible mutations of the MEN1 gene in 23 cutaneous melanoma and 17 melanoma metastases." (PMID 36428828, 2022). "MEN1 gene, respective menin involvement has also been found in melanomas, but the association with MEN1 remains debatable." (PMID 36428828, 2022). "Moreover, genetic analysis of two MEN1 family members affected by melanoma revealed the presence of specific point mutations within the MEN1 gene." (PMID 38891107, 2024). "Furthermore, we report here two families with melanoma in which at least two first-degree family members tested positive for MEN1 mutations." (PMID 38891107, 2024). "Moreover, our study suggested that all patients testing positive for MEN1 mutations are at risk of melanoma; because this may be a deadly disease, these patients should be monitored for melanoma." (PMID 38891107, 2024). "However, other studies were unable to find MEN1 mutations in melanomas." (PMID 36428828, 2022). "In contrast, in the cholangiocarcinoma cell line SK-Hep1 and the malignant melanoma cell line A375, MEN1-KD inhibited the transcription of these genes." (PMID 40057469, 2025). "We began addressing this by first reducing MEN1 WT expression levels in WM278 melanoma cells using a shRNA-mediated knockdown (KD) strategy." (PMID 38891107, 2024). "Another study suggested that multiple melanoma tumor suppressors are localized on chromosome 11q, which includes the MEN1 region." (PMID 38891107, 2024). "The results from our in vivo preclinical models clearly indicate that MEN1 knockout leads to increased primary melanoma tumor growth." (PMID 38891107, 2024). "The significant increases in primary tumor formation observed in vivo upon MEN1 silencing further emphasize the central role of MEN1 in mediating tumor suppression in melanoma." (PMID 38891107, 2024). "Taken together, these results indicate that the loss of TGFβ tumor-suppressive responses in patients harboring MEN1 mutations leading to MEN1 degradation could be circumvented by blocking the proteasome degradation pathway, thereby offering new therapeutic opportunities for patients with melanoma." (PMID 38891107, 2024). "For this purpose, we generated MEN1 knockout models in three different melanoma cell lines (WM1232, BLM and WM278)." (PMID 38891107, 2024). "Taken together, these results strongly suggest that MEN1 acts downstream of the TGFβ signaling pathway to regulate cell-cycle arrest and apoptosis in melanoma." (PMID 38891107, 2024). "To this end, we generated MEN1 CRISPR-KOs in WM278 melanoma cells and assessed their effects on colony formation assay in vitro." (PMID 38891107, 2024).
melanoma (continued). "Loss of heterozygosity (LOH) of chromosome 11q13 (the MEN1 gene locus) was detected in six melanoma tumors, and deletion of the MEN1 locus was found in 19 patients with sporadic metastatic melanoma." (PMID 38891107, 2024). "For this purpose, we used the melanoma cell lines engineered above (cells depleted of endogenous MEN1 or overexpressing WT or mutant MEN1)." (PMID 38891107, 2024). "Other non-melanoma cutaneous cancers, such as basal cell carcinoma, squamous cell carcinoma, or T-cell lymphoma have also been observed in MEN1, but the level of statistical significance is extremely low, thus, most probably, the association was incidental." (PMID 36428828, 2022). "The findings include the role of MEN1 gene in tumor suppression of melanoma and the role of menin in inhibiting melanoma cell migration and proliferation." (PMID 36428828, 2022). "Only one somatic MEN1 mutation was identified in a sporadic tumor whereas LOH including the MEN1 gene locus was found in 4/19 (21%) sporadic melanomas." (PMID 36325452, 2022). "Two of the four studies primarily focusing on the dermatologic manifestations of MEN1 reported patients with melanoma: 2/48 (4%) in an NIH study and 1/9 (11%) in the small Spanish study." (PMID 36325452, 2022). "Unfortunately, in this study, the authors were unable to test for LOH in the melanomas from MEN1 patients." (PMID 36325452, 2022). "We next investigated whether the tumor-suppressive effects of the MEN1 pathway could lead to the inhibition of tumor formation in vivo using preclinical models of melanoma." (PMID 38891107, 2024). "Using pharmacological inhibitors and RNA interference strategies, we showed that we could efficiently restore both MEN1 gene expression and TGFβ signaling in melanoma cells." (PMID 38891107, 2024). "TGFβ significantly upregulated MEN1 at both protein and mRNA levels in all melanoma cell lines." (PMID 38891107, 2024). "Interestingly, multiple potential melanoma tumor suppressors are localized on chromosome 11q, which includes the MEN1 region (located on chromosome 11q13)." (PMID 38891107, 2024). "For this purpose, we first investigated whether TGFβ could regulate MEN1 gene expression in melanoma." (PMID 38891107, 2024). "Taken together, these results highlight MEN1 as a novel TGFβ/Smad target in melanoma, further suggesting that MEN1 may act downstream of TGFβ in melanoma cells." (PMID 38891107, 2024). "Despite potential menin involvement in the development of melanoma, germline MEN1 mutations are not prone to this malignancy, as, for instance, has been found with other genes such as CDKN2A." (PMID 36428828, 2022). "The 70-year-old male patient, known with MEN1 for 10 years, was diagnosed with three different cutaneous tumors, one of benign origin (papillomatosis confluens et reticularis), and two malignant tumors (a melanoma and a squamous cell carcinoma)." (PMID 36428828, 2022). "Other hormonal dysfunctions involving growth factors, growth hormone–IGF-1 axes, or estrogens/estrogen receptor status have been reported in melanoma without a clear connection to endocrine tumors underlying MEN1." (PMID 36428828, 2022). "More recently, there has been some published evidence to suggest that MEN1 may suppress the malignant phenotype of melanoma cells and act as a melanoma tumor suppressor." (PMID 36325452, 2022). "Therefore, there are insufficient data looking for somatic alterations in the MEN1 gene in melanomas removed from MEN1 patients." (PMID 36325452, 2022). "Several publications have reported the diagnosis of melanoma in MEN1 patients." (PMID 36325452, 2022). "Thus, new therapeutic strategies aimed at activating the TGFβ/MEN1 signaling pathway could prove useful for melanoma patients at different stages of the disease, including primary tumor formation." (PMID 38891107, 2024).